NR2E3 (nuclear receptor subfamily 2 group E member 3)
Diseases named in the same sentence as NR2E3 in open-access papers (continued):
Sharing a sentence is not in itself a finding about the gene and the disease.
cancer (continued). "The observation that high expression levels of NR2E3 correlate with superior prognosis in various cancer types raises the question of how to activate NR2E3 for therapeutic benefit." (PMID 39809731, 2025). "By regulating pathways such as IFN-α, MYC, E2F, and ATP production, NR2E3 emerges as a versatile tumor suppressor with broad implications in cancer biology." (PMID 39809731, 2025). "Overall, our findings suggest that NR2E3 holds promise as a therapeutic target for cancer treatment, offering new avenues for effective anti-cancer strategies." (PMID 39809731, 2025). "We further explore drug repurposing screens of FDA-approved anti-cancer drugs to develop NR2E3-targeted combinatorial treatments, such as the 11a-Romidepsin combination in HeLa cells." (PMID 39809731, 2025). "This approach holds great potential for identifying additional NR2E3-targeted combinatorial treatments for various cancer types." (PMID 39809731, 2025). "Scratch, Boyden chamber, and sphere formation assays were conducted to assess the impact of NR2E3 depletion on cancer cell migration, invasion, and self‐renewal capacity." (PMID 38790135, 2024). "Further analysis, such as KEGG gene pathway analysis using genes near KO II‐specific FAIRE peaks, revealed that the “pathways in cancer” is the most significantly enriched signaling pathway in NR2E3‐depleted cells." (PMID 38790135, 2024). "The low levels of NR1D1 and NR2E3 expression in RB are consistent with previous findings in other cancers." (PMID 38480634, 2024). "Our results add Nr2e3 and Ezh2 to the recently identified regulatory interplay between Jag1 and 17beta-estradiol that is important in cancer and other tissue specific disorders including retinal diseases." (PMID 28386079, 2017). "Our future studies will further explore the role of Nr2e3 in cancer and regulation of metastasis via miRNAs and NHRs." (PMID 28386079, 2017). "This underscores the potential therapeutic value of activating NR2E3 in cancer treatment." (PMID 39809731, 2025). "Regardless of the FL or short, high NR2E3 RNA levels when normalizing to β-actin were linked to superior disease-free and overall survivals across 33 cancer types when combined." (PMID 39809731, 2025). "Since the short arises naturally from alternative RNA splicing, our findings suggest that investigating the imbalance between both isoforms may provide insights into NR2E3’s roles in cancer." (PMID 39809731, 2025). "Additionally, both NR2E3 and 11a exhibit similar multifaceted anti-cancer properties, underscoring NR2E3 as a novel molecular vulnerability in cancer cells." (PMID 39809731, 2025). "Additionally, the statistical tool GEPIA correlated NR2E3 RNA levels with the overall and disease-free survivals of cancer patients in the TCGA database." (PMID 39809731, 2025). "Furthermore, NR2E3 depletion increased proliferation and resistance to sorafenib, a cancer drug used to treat advanced HCC." (PMID 38790135, 2024). "Indeed, NR2E3 warrants comprehensive exploration in the context of cancer studies." (PMID 39809731, 2025).
cancer (continued). "Additionally, we identified that NR2E3 depletion in human cancer cells increased cell proliferation, migration, invasion capacity, tumor sphere formation, and xenografted tumor formation, all accompanied by enhanced activation of the β‐catenin signaling pathway." (PMID 38790135, 2024). "Our study found that NR2E3 may serve as a tumor suppressor and a favorable prognostic indicator in HCC and possibly in other cancer types." (PMID 38790135, 2024).
tumor (6 papers, 2017 to 2025). "There was significant increase in the number and the size of tumor formation in the Nr2e3−/− mice at both 24‐ and 46‐week time points, demonstrating that NR2E3 loss facilitated HCC formation." (PMID 38790135, 2024). "In our study, NR1D1 and NR2E3, which play a critical role in the development and differentiation of photoreceptors, showed low expression levels in RB tumor tissues compared to retina and were strongly associated with invasive clinicopathological features of RB." (PMID 38480634, 2024). "Additionally, an increased number of tumor spheres or aggregation was observed in an anchorage‐independent sphere formation assay, indicating enhanced self‐renewal capacity with NR2E3 loss." (PMID 38790135, 2024). "In contrast, the short isoform of NR2E3 behaves dominantly negatively to the full-length isoform, exhibiting tumor-promoting effects instead." (PMID 39809731, 2025). "The orphan nuclear receptor NR2E3 has emerged as a potential tumor suppressor, yet its precise mechanisms in tumorigenesis require further investigation." (PMID 39809731, 2025). "To identify the key pathways contributing to accelerated tumor formation in Nr2e3−/− mice, we performed RNA‐seq analysis using both wild‐type and Nr2e3−/− liver tumor tissues." (PMID 38790135, 2024). "In summary, NR2E3 is a novel tumor suppressor with a significant prognostic value, maintaining epigenetic homeostasis to suppress the Wnt/β‐catenin signaling pathway that promotes HCC development." (PMID 38790135, 2024). "The KO II‐xenografted tumors showed enhanced tumor growth compared to the CT‐xenografted tumors, supporting the tumor‐suppressive role of NR2E3." (PMID 38790135, 2024). "The expression of NR1D1 and NR2E3 were found to be lower in RB tumor tissues than in normal and non-tumor retinal tissues." (PMID 38480634, 2024). "In conclusion, this study identifies NR2E3 as a novel tumor‐suppressive epigenetic regulator that suppresses HCC development." (PMID 38790135, 2024). "NR2E3 loss accelerates HCC with increased Wnt/β‐catenin activity, highlighting its novel tumor suppressor function in HCC." (PMID 38790135, 2024). "The expression levels of NR1D1 (P = 0.004) and NR2E3 (P = 0.024) were significantly lower in RB tumor tissues than in normal retina." (PMID 38480634, 2024). "Despite the substantial evidence supporting NR2E3's role as a tumor suppressor with epigenetic regulatory functions in HCC, this study has some limitations." (PMID 38790135, 2024). "We have concentrated our efforts on elucidating the tumor-suppressing roles of NR2E3." (PMID 39809731, 2025). "Moreover, NR2E3 expression was found to be diminished in tumor tissues and reduced with tumor stage progression, not only in HCC but also in multiple tumor types when we analyze TCGA data." (PMID 38790135, 2024). "In this research, we conveyed immunohistochemical (IHC) staining to examine the expression of NR1D1 and NR2E3 in the tumor tissues of RB patients, and explored their correlation with clinical and pathological features of RB, including disease stages, infiltration of the choroid and optic nerve." (PMID 38480634, 2024). "Additionally, further exploration of the biological mechanisms underlying RB progression is necessary, particularly to determine if NR1D1 and NR2E3 serve as early indicators of more aggressive RB or if these genes are downregulated as the tumor grows." (PMID 38480634, 2024).
tumor (continued). "Notably, high NR2E3 expression emerged as a critical determinant correlated with favorable clinical outcomes, regardless of high expression levels of Sp1, β‐catenin, or p300, reinforcing NR2E3's role as a good prognostic indicator and tumor suppressor." (PMID 38790135, 2024). "GSEA analysis revealed that low NR2E3 expression in HCC patients was associated with a heightened activation of the Wnt/β‐catenin signaling pathway and, notably, reduced NR2E3 expression extended beyond liver tumors, as we observed similar decreases in other tumor types compared to normal tissues." (PMID 38790135, 2024). "In normal retina and non-tumor retina tissues, NR1D1 and NR2E3 were expressed in the cell nucleus of the outer nuclear layer, inner nuclear layer, and ganglion cell layer, especially high-expressed in the outer nuclear layer." (PMID 38480634, 2024). "Similar results were achieved in NR2E3 staining, which showed the average AOD of 0.218 ± 0.027, 0.238 ± 0.025, and 0.230 ± 0.029 in RB tissue, normal retina, and non-tumor retina in RB patients, respectively." (PMID 38480634, 2024). "In addition, the expression levels of rod-enriched genes, including NRL, NR2E3, CNGA1, and PDE6G, were depleted in organoids, consistent with tumor, but high in normal retina, where rods outnumber cones." (PMID 30353124, 2018).
infection (4 papers, 2012 to 2025). The state of being infected such as from the introduction of a foreign agent such as serum, vaccine, antigenic substance or organism. "Tet2 protein also significantly decreased in Nr2e3KO cells but increased in rescued cells after the infection with Nr2e3 lentivirus." (PMID 38881534, 2024).
genetic disorder (2 papers, 2017 to 2022). "Defects in both Nrl and Nr2e3 lead to non-functional rods in mice and the genetic disorder of S-cone syndrome is attributed to loss of Nr2e3 in humans and results in a fate switch from rods to S-cones." (PMID 36172288, 2022).
NR2E3 also shares sentences with these, for which no sentence is quoted: bacterial infection (3 papers); retinal (3); achromatopsia (2); autosomal recessive retinitis pigmentosa (2); Chorioretinal atrophy (2); cone-rod dystrophies (2); adrenal hypoplasia congenita (1); age-related macular degeneration (1); Bardet-Biedl syndrome (1); choroideremia (1); colon cancer (1); complication (1); diabetic nephropathy (1); diabetic retinopathy (1); glaucoma (1); hypogonadism (1); lentivirus infection (1); lipoprotein lipase deficiency (1); liver diseases (1); lung carcinoma (1); macular oedema (1); medulloblastoma (1); melanoma (1); myopia (1); neurodegenerative disease (1); ovarian carcinoma (1); pancreatic cancer (1); recessive retinitis pigmentosa (1); retinitis pigmentosa 1 (1); retinitis pigmentosa 37 (1).
A further 6 diseases each share a sentence with NR2E3 in 1 paper.